PRG4 (proteoglycan 4)
Diseases named in the same sentence as PRG4 in open-access papers (continued):
Sharing a sentence is not in itself a finding about the gene and the disease.
Arthritis (10 papers, 2015 to 2025). Inflammation of a joint. "A hallmark of cells comprising the superficial zone of articular cartilage is their expression of lubricin, encoded by the Prg4 gene, that lubricates the joint and protects against the development of arthritis." (PMID 33712729, 2021). "Previous studies have reported decreased PRG4 expression in drug-induced arthritis and post-traumatic OA models." (PMID 38719877, 2024). "Patients with arthritis have increased PRG4 sialylation, which may lead to altered PRG4 glycosylation." (PMID 40149669, 2025). "CREB5 was also found as a transcription factor to regulate prg4 expression and prevent arthritis." (PMID 35773668, 2022). "Quantification of jaw joint defects using an Osteoarthritis Research Society International (OARSI) scoring system that we modified for zebrafish confirmed that joint defects increased in severity during aging, consistent with the progressive arthritis seen in Prg4-/- mice and patients with CACP." (PMID 27434666, 2016). "Interestingly, during Mir221/222 overexpression in arthritis, the expression of ECM-related molecules in SFs was found altered and, more specifically, Prg4 and the integrin component Itga3 were downregulated." (PMID 39235454, 2024).
breast carcinoma (8 papers, 2016 to 2025). "PRG4 suppresses TGFβ-induced invasiveness of breast cancer cells by inhibiting the cell surface cluster of differentiation 44 (CD44) signaling." (PMID 37621676, 2023). "In breast cancer, PRG4 inhibitor demonstrated a higher fold change difference between the early stage of breast cancer compared to controls, suppressing cell migration and invasiveness." (PMID 32564237, 2020). "Recently, it was demonstrated that the human recombinant form of the proteoglycan 4 (PRG4) inhibits TGFβ-mediated invasiveness of breast cancer cells by binding to CD44 and affecting its downstream signaling pathway." (PMID 33199679, 2020). "Further analysis by gel-based proteomics detected significant inverse altered abundance of proteoglycan 4 and plasma protease C1 inhibitor in both the early stages of breast cancer patients compared to the controls." (PMID 26890881, 2016). "In addition, ANGPT1, PRG4, and RBMS3 were found to be mutated within a portion of the TCGA breast cancer samples." (PMID 37621676, 2023). "The finding that anti-PRG4 mAb 4D6, which specifically recognizes PRG4 based on immunoblotting and immunohistochemistry analyses, interferes with the ability of rhPRG4 to suppress invasive growth of breast cancer cell-derived organoids suggests that mAb 4D6 acts as an PRG4-neutralizing antibody." (PMID 31361756, 2019). "Our data suggests that the ratio of serum proteoglycan 4 to protease C1 inhibitor may be used for screening of early breast cancer although this requires further validation in clinically representative populations." (PMID 26890881, 2016). "In addition, PRG4 has been demonstrated to have anti-inflammatory properties, and it may suppress breast cancer cell invasion." (PMID 33670198, 2021). "Here, we report that a full-length recombinant human PRG4 (rhPRG4) suppresses the ability of the secreted protein transforming growth factor beta (TGFβ) to induce phenotypic disruption of three-dimensional human breast cancer cell-derived organoids by reducing ligand-induced cell invasion." (PMID 31361756, 2019). "Hence, proteoglycan 4 may be one of the heavily O-glycosylated proteins whose levels were earlier shown to be elevated in the serum samples of patients with breast cancer." (PMID 26890881, 2016). "Using this methodology, we identified nine proteins—FN1, VWF, PRG4, MMP9, CLU, PRDX6, PPBP (CXCL7), APOC1, and CHL1—that were robustly quantified in serum and showed statistically significant differences between breast cancer patients and healthy controls." (PMID 40940928, 2025). "The role of VWF, PRG4, and PPBP on breast cancer is predicted to be on tumor progression and metastasis." (PMID 37268731, 2023). "While, the intensity of proteoglycan 4 appeared significantly elevated in serum PCA isolates of both stage 0 and stage I breast cancer samples, the bands of plasma protease C1 inhibitor proteins appeared significantly more intense in those of the controls." (PMID 26890881, 2016). "We found that incubation of the 3D cultures with the anti-PRG4 mAb 4D6, but not with mouse IgG control, decreased the ability of rhPRG4 to suppress TGFβ-induced deformation in the growth of the 3D-breast cancer cell-derived organoids." (PMID 31361756, 2019). "By subjecting CGB lectin-captured glycoprotein fractions of serum PCA isolates of the stage 0 and stage I breast cancer patients and those of controls to SDS-PAGE, we were able to further show that the intensities of proteoglycan 4 and plasma protease C1 inhibitor bands were differently altered." (PMID 26890881, 2016).
Camptodactyly (8 papers, 2008 to 2023). The distal interphalangeal joint and/or the proximal interphalangeal joint of the fingers or toes cannot be extended to 180 degrees by either active or passive extension. "Mice that have been genetically engineered to lack lubricin (Prg4-/-) developed camptodactyly, synovial hyperplasia, and cartilage deterioration, similar to humans with CACP." (PMID 25642942, 2015). "Human patients with camptodactyly-arthropathy–coxa vara–pericarditis (CACP) syndrome who lack functional lubricin and Prg4 knockout mice develop severe, early-onset polyarthropathy, demonstrating the significance of lubricin in chondroprotection and joint homeostasis." (PMID 33028842, 2020). "Camptodactyly-arthropathy-coxa vara-pericarditis (CACP) syndrome, caused by biallelic pathogenic mutations in the proteoglycan 4 (PRG4) gene, is characterized by early-onset camptodactyly, noninflammatory arthropathy, coxa vara deformity, and rarely, pericardial effusion." (PMID 36694203, 2023).
atherosclerosis (5 papers, 2020 to 2023). A disease characterized by the build-up of fatty material and calcium deposition in the arterial wall resulting in partial or complete occlusion of the arterial lumen. "Combined, we associate plaque expression levels of PRG4 with clinical surrogate markers of advanced atherosclerosis and plaque phenotype." (PMID 34063989, 2021). "Taken together, our data from murine studies illustrate the early enrichment and continuous role of PRG4 via osteogenic expression patterns in SMCs during the process of intimal remodeling, towards macro-calcification typical for late-stage atherosclerosis." (PMID 34063989, 2021). "Functionally, we investigated the role of PRG4 by in vivo studies of intimal hyperplasia in response to vascular injury in rats and mice, as well as studies of calcification in mouse atherosclerosis." (PMID 34063989, 2021). "We also show that PRG4 and SOX9 induction preceded the formation of macro-calcification nodules in the mouse model of calcific atherosclerosis, supporting the role of PRG4 in early osteogenic modulation during atheroprogression." (PMID 34063989, 2021). "Together, these results support the connection between an osteogenic switch of SMCs and PRG4 upregulation under the influence of prevalent stimuli in atherosclerosis." (PMID 34063989, 2021). "Whereas PRG4 expression has been shown to be important for cell survival (i.e., in chondrocytes), the role of endogenous vs. extracellular PRG4 in atherosclerosis is unknown." (PMID 34063989, 2021). "The inhibition of SMC migration and proliferation suggests that PRG4 may both influence calcification and SMC phenotype in atherosclerosis." (PMID 34063989, 2021). "Thus, Prg4 and NONMMUT003096 might have effect on macrophage function in CIH-aggravated atherosclerosis." (PMID 32328084, 2020).
Hepatic steatosis (5 papers, 2020 to 2025). Steatosis is a term used to denote lipid accumulation within hepatocytes. "Knockout PRG4 mice exhibit better glucose handling when fed a high-fat diet and are protected from hepatic steatosis and white adipose tissue inflammation." (PMID 34441954, 2021). "Furthermore, the glucose intolerance-related protein PRG4, which affects hepatic steatosis and was found to be down-regulated after bariatric surgery, showed the same significant change in our study." (PMID 38182717, 2024). "PRG4 KO mice are protected from high fat diet-induced hepatic steatosis and exhibit an improved glucose tolerance and lower degree of white adipose tissue inflammation, suggesting a role for PRG4 in the regulation of nutritional homeostasis and inflammation in fatty liver disease." (PMID 33262757, 2020). "In participants with severe hepatic steatosis (n = 43), subgroup analysis showed increased COL18A1, AFM, PRG4, and INHBE and decreased C4A and APOA1." (PMID 41354933, 2025).
synovitis (5 papers, 2020 to 2025). Inflammation of a synovial membrane. "Taken together, this suggests that dysfunction in PRG4 signaling is more pronounced in high-grade synovitis and may be causally related to the excess inflammation seen in these specimens." (PMID 41282165, 2025). "Targeting the downstream events of PRG4 loss is potentially therapeutic in OA synovitis." (PMID 41282165, 2025). "We also investigated whether PRG4 signaling dysregulation was associated with synovitis in patients with OA." (PMID 41282165, 2025). "We hypothesized that A) CD44 genetic ablation protected against development of synovitis in vivo following Prg4 inactivation, and B) dysregulation of Prg4 signaling was associated with high-grade synovitis." (PMID 41282165, 2025). "Dysfunction in PRG4 signaling, demonstrated by lower tissue levels of PRG4 along with higher CD44, XO and HIF-1α, was associated with high-grade synovitis." (PMID 41282165, 2025). "PRG4 staining decreased in both high and low-grade synovitis and PRG4 staining in high-grade synovitis specimens was lower than low-grade synovitis specimens (p < 0.001)." (PMID 41282165, 2025). "In our study, we identified that PRG4 synovial content had an inverse relationship with synovitis grade." (PMID 41282165, 2025). "Overall, high-grade synovitis specimens were more likely to have lower PRG4 content, along with higher CD44, XO and HIF-1α contents compared to low-grade synovitis specimens." (PMID 41282165, 2025). "As such, it is expected that the enhanced TLR2 and TLR4 receptor signaling in the absence of PRG4 would propagate synovitis in Prg4 null mice." (PMID 32404156, 2020).
gout (3 papers, 2019 to 2023). A condition characterized by painful swelling of the joints, which is caused by deposition of urate crystals. "The anti-inflammatory activity of rhPRG4 in monocytes is partially mediated by PP2A, and in vivo, PRG4 plays a role in regulating the trafficking of immune cells into the site of a gout flare." (PMID 34992596, 2021). "PRG4 may also play a significant role in mediating the resolution of acute gout inflammation." (PMID 34992596, 2021).
hepatocellular carcinoma (3 papers, 2022 to 2025). A malignant tumor that arises from hepatocytes. "The data presented herein indicate that PRG4 has the potential to enhance the anti-tumor efficacy of regorafenib in the treatment of hepatocellular carcinoma (HCC), without necessitating dose escalation and thereby mitigating the risk of associated side effects." (PMID 41327374, 2025).
Obesity (3 papers, 2021 to 2025). Accumulation of substantial excess body fat. "However, some proteins were primarily affected by other factors: SHBG by age and obesity; PRG4 by obesity; and IGF1 and RBP4 by age." (PMID 39972214, 2025). "The regulation and roles of PRG4 in obesity are largely unknown and require further work to be delineated." (PMID 34441954, 2021). "BMI-predictive proteins included established obesity markers and obesity-related proteins, including adiponectin, CRP, IGFBP1, IGFBP2, PRG4, SHBG, apolipoproteins (APOA4, APOF) and inflammatory response proteins (A2M, APCS, LBP, HSPG2, HP, AOC3, ITGB1, VNN1)." (PMID 39972214, 2025).
Sepsis (3 papers, 2022 to 2024). Sepsis is defined as life-threatening organ dysfunction caused by a dysregulated host response to infection. "Besides, PRG4 has recently been suggested to serve as a potential therapeutic and biomarker in sepsis." (PMID 38020105, 2023). "We have shown previously that PRG4, a protein that behaves as an APR in many inflammatory models, gets deposited in the liver vasculature in this sepsis model of S. aureus bacteremia by 24 h." (PMID 35913192, 2022). "Although a role in sepsis has not been previously demonstrated, PRG4 has been established as an anti-inflammatory competitor for hyaluronic acid binding and it could therefore influence how immune cells interact with activated ECs." (PMID 38020105, 2023).
Alzheimer disease (2 papers, 2022 to 2023). A progressive, neurodegenerative disease characterized by loss of function and death of nerve cells in several areas of the brain leading to loss of cognitive function such as memory and language. "Furthermore, five proteins (IGHV3.9, PRG4, VWF, ALB and CST3) were significantly associated with ESR values, with CST3, a protein active in neurodegenerative (Alzheimer’s Disease) and demyelinating (multiple sclerosis) neurological conditions." (PMID 35033099, 2022).
aortic valve calcification (2 papers, 2020 to 2022). "Among DEGs not related to humoral immunity many overlap with those already implicated in aortic valve calcification, these include TNC, PRG4, COL11A1, SMOC2, FN1, and OGN." (PMID 36437309, 2022). "However, the role of PRG4 in the context of AVS and aortic valve calcification has not yet been determined." (PMID 32168892, 2020).
liver cancer (2 papers, 2020 to 2022). An epithelial or non-epithelial malignant neoplasm that arises from the liver. "Western blot analysis showed that PRG4 may affect the migration ability of liver cancer cells by regulating EMT activity." (PMID 36439456, 2022).
lymphedema (2 papers, 2022 to 2023). Excess fluid collection in tissues, causing swelling. "Among them, the PRG4+/CLEC3B+ ASC subpopulation c3 was significantly expanded in lymphedema and related to adipose tissue fibrosis." (PMID 35725971, 2022). "Through immunofluorescence staining, we confirmed the presence of the PRG4+ ASCs in subcutaneous adipose tissues of healthy donors and lymphedema patients." (PMID 35725971, 2022). "Furthermore, we pinpointed the ASC subpopulation that was closely associated with the pathophysiology of lymphedema, i.e., c3 (PRG4+/CLEC3B+ ASCs), which was significantly expanded in lymphedema." (PMID 35725971, 2022).
melanoma (2 papers, 2022 to 2024). A malignant, usually aggressive tumor composed of atypical, neoplastic melanocytes. "In the setting of melanoma diagnosis, PRG4 has been identified as one of the most significantly mutated genes in a genome sequencing of 25 metastatic melanoma tumours." (PMID 39405606, 2024). "Frequent PREX2 and PRG4 mutations was observed in melanoma and mutant PREX2 accelerated tumor formation." (PMID 35449126, 2022). "However, this study has identified other proteins in melanoma patient-derived EVs using machine learning algorithms, including PRG4 and APOC4, that have been linked to melanoma pathogenesis and progression." (PMID 39405606, 2024). "Proteins (APOC4, PRG4, PLG, TNC, VWF and SERPIND1) and metabolites (lyso PC a C18:2, PC ae C44:3) previously associated with melanoma pathogenesis were identified as relevant in differentiating between disease stages." (PMID 39405606, 2024). "•Proteins linked to melanoma development (PRG4, APOC4, SERPIND1, VWF, TNC and PLG) were identified in the plasma-derived EVs of patients with melanoma." (PMID 39405606, 2024). "PRG4 has also been identified as a gene whose expression can be used distinguish primary melanomas from subcutaneous metastases, in their interrogation of The Cancer Genome Atlas (TCGA)." (PMID 39405606, 2024). "A grid search was then performed, and it was found that the best performing combination of features in terms of accuracy to distinguish the plasma-derived EV samples from patients with melanoma compared to healthy controls, was a signature consisting of PRG4 and PC ae C34:3." (PMID 39405606, 2024). "Three proteins were commonly identified using the three algorithms as relevant in classifying EVs derived from patients with a melanoma diagnosis compared to those from healthy controls: specifically, Proteoglycan 4 (PRG4), Apolipoprotein C4 (APOC4) and Haptoglobin-Related Protein (HPR)." (PMID 39405606, 2024). "A grid search demonstrated that APOC4 and PRG4 could be used to distinguish melanoma patient EVs from healthy control with an accuracy of 73.4 %." (PMID 39405606, 2024).
pericarditis (2 papers, 2018 to 2021). An inflammatory process affecting the pericardium. "For pericarditis, we identified PRG4 gene (proteoglycan 4) as the only gene associated with pericarditis according to MetaCore methods and data in the biomedical literature." (PMID 34696294, 2021). "This association between PRG4 and pericarditis is based on a mutational study indicating that mutations in PRG4 gene on chromosome 1 result in camptodactyly arthropathy-coxa vara-pericarditis syndrome." (PMID 34696294, 2021).
steatosis (2 papers, 2020 to 2025). Increased lipid within the cytoplasm of cells. "Only PRG4 and ECM-1 demonstrated protection from steatosis and inflammation in high fat diet mouse models, and an inversed correlation with severity of liver fibrosis, respectively." (PMID 33262757, 2020).
acute synovitis (1 paper, 2021). An acute inflammation of a synovial membrane. "Our objectives were to study the PRG4’s importance to macrophage homeostatic regulation in the synovium and infiltration of pro-inflammatory macrophages in acute synovitis and investigate whether macrophages mediated synovial fibrosis in Prg4 gene-trap (Prg4GT/GT) murine knee joints." (PMID 34521469, 2021).
bacteremia (1 paper, 2019). "Here we report that PRG4 gene expression is rapidly induced during MRSA bacteremia, resulting in its secretion and abundant vascular deposition in the liver." (PMID 31604940, 2019).
chondrosarcoma (1 paper, 2021). A malignant cartilaginous matrix-producing mesenchymal neoplasm arising from the bone and soft tissue. "To begin to determine whether Creb5 can confer competence for Prg4 expression in growth plate-like chondrocytes, we infected either a human chondrosarcoma cell line (SW1353) or an immortalized human costal chondrocyte cell line (C-28/I2;49) with lentivirus encoding either EGFP or Creb5." (PMID 33712729, 2021).
colitis (1 paper, 2022). Inflammation of the colon. "In addition, proteoglycan 4 is a protein that is critical for the virulence factor binding to the cell surface, so it plays an important role in colitis." (PMID 36204290, 2022).
dry eye (1 paper, 2023). "Additionally, research indicated that degradation of PRG4 by CTSS might be linked with diminished ocular surface lubrication in SS, explaining the dry eye symptom." (PMID 37727764, 2023).
endothelial dysfunction (1 paper, 2022). In vascular diseases, endothelial dysfunction is a systemic pathological state of the endothelium (the inner lining of blood vessels) and can be broadly defined as an imbalance between vasodilating and vasoconstricting substances produced by (or acting on) the endothelium. "Finally, the finding of other proteoglycans differentially regulated in C2 and/or C3, such as SDC and proteoglycan 4 (PRG4), suggest a close relationship between the glycocalyx, endothelial dysfunction and pre-eclampsia." (PMID 35144530, 2022).
Insulin resistance (1 paper, 2024). Increased resistance towards insulin, that is, diminished effectiveness of insulin in reducing blood glucose levels. "Six proteins function in regulating glucose homeostasis, insulin resistance, and β-cell function, including SHBG, FETUB, PRG4, GSN, CFD, and TF, among which SHBG and FETUB are markers of insulin sensitivity and the expression of TF in adipose tissue is positively associated with insulin sensitivity." (PMID 38182717, 2024).